NECTIN4 (nectin cell adhesion molecule 4)
Diseases named in the same sentence as NECTIN4 in open-access papers (continued):
Sharing a sentence is not in itself a finding about the gene and the disease.
tumor (continued). "The interaction between soluble Nectin-4 and integrin β4 on endothelial cells can regulate the transcriptional activity of Src, PI3K, AKT, and endothelial NO synthase, inducing the formation of NO mediated by the PI3K/AKT signaling pathway, thereby promoting tumor angiogenesis." (PMID 40697656, 2025). "Interestingly, high Nectin‐4 expression in the primary tumour strongly correlated with high expression in LN metastases, but Nectin‐4 positivity was also frequently seen in cases with no Nectin‐4 expression in the primary tumour." (PMID 39801278, 2025). "By leveraging the specificity of [68Ga]AJ647 for Nectin-4, we demonstrated the ability to dynamically quantify target engagement across a range of preclinical models, bridging critical gaps in current ADC development strategies and enabling a deeper understanding of drug-tumor interactions." (PMID 39763905, 2024). "EV is taken up by the body after binding to Nectin-4, which is a Ca2+-independent immunoglobulin-like protein that is highly expressed on the surface of cancer cells; subsequently, MMAE is released into the cells to inhibit cell division, induce apoptosis, and exert its anti-tumor effect." (PMID 39123376, 2024). "Therefore, theoretically, the inclusion of Cy7 dye does not impact the specific tumor-targeting capability of Nectin-4 NDC." (PMID 38755613, 2024). "Nectin-4 has a critical role in cancer cell proliferation and metastasis via the proliferation of cancer cells by activating the phosphatidylinositol-3 kinase (PI3K)/Akt pathway and epithelial–mesenchymal transition (EMT)-related signaling, which contributes to the metastasis of tumor cells." (PMID 37345201, 2023). "For example, expressions of HER2, TROP2, EGFR, EpCAM, and nectin 4 are also observed to some extent in non-malignant cells, however because of their overexpression in tumor cells has made them suitable as target antigens in designing ADCs for the solid tumors and currently approved by the FDA." (PMID 37671162, 2023). "As our cohort did not include patients with metastatic UC, serum Nectin-4 might be unsuitable for correlation analysis between tumor expression and serum levels." (PMID 37174031, 2023). "In addition, it has also been reported that Nectin-4 could activate the phosphoinositide 3-kinase (PI3K)/protein kinase B (AKT) pathway and is related to tumor proliferation, metastasis, and angiogenesis in the gallbladder and gastric cancer." (PMID 35953862, 2022). "In addition, because of high Nectin-4 expression in urothelial tumor biopsy samples, prescreening of Nectin-4 expression in tumor samples before EV administration is not necessary, which eliminates diagnostic barriers for EV administration in UC." (PMID 32031899, 2020). "Co-expression of Nectin-4 and active TACE in a tumor may not be sufficient to induce the release of detectable levels of Nectin-4 in the serum of patients with non-MBC." (PMID 17474988, 2007). "Mice exhibiting low Nectin-4 engagement post-treatment showed reduced tumor growth inhibition, regardless of dose, suggesting that target engagement itself may serve as a more reliable early biomarker of therapeutic efficacy than dose or Nectin-4 expression alone." (PMID 39763905, 2024). "This could be why Nectin-4 does not show prognostic value in all tumor types." (PMID 38606099, 2024). "Although expression of Nectin-4, Kallikrein-10, and Kallikrein-13 have been reported to be elevated in ovarian cancer tumor tissues and serum or ascites, peptides for these 3 biomarkers were only observed in the Pap test fluid, but not in the tumor tissue or swab." (PMID 33413078, 2021). "In contrast to the results described here, an earlier study on Nectin-4 using a smaller cohort, described no expression in normal breast epithelium, but expression in 61% of the ductal cancers examined and that nearly all ER/PR negative tumours expressed Nectin-4." (PMID 24386110, 2013).
tumor (continued). "Patients with Nectin‐4‐positive and ABC transporter‐negative tumours had the longest PFS, underscoring the prognostic significance of these biomarkers." (PMID 39877564, 2025). "When stratified into four groups based on Nectin‐4 and ABC transporter expression, patients with Nectin‐4‐positive and ABC transporter‐negative tumours had the longest PFS (p = 0.002)." (PMID 39877564, 2025). "The serum nectin-4 was elevated in LC patients and correlated with NSCLC stage, the tumor size and metastasis, but was not prognostic." (PMID 37568798, 2023). "L4 yielded comparable staining results to the commercial anti-nectin-4 antibody HPA010775 (Sigma-Aldrich), with minimal background on the non-tumor tissues (NT) and strong signals on the tumor tissues (T1-T5) of different molecular subtypes." (PMID 38288120, 2023). "The anti-tumor effect of the MV vaccine strain was demonstrated using a NSCLC cell line (A549), which does not express Nectin-4." (PMID 26317644, 2015). "None of the tumor cell lines studied in our experiments exhibited CD150/SLAM expression and Nectin-4 was only found to be weakly expressed on HT29 cells as determined by flow cytometry." (PMID 23586034, 2013). "Taken together, these data demonstrate that across multiple UC cell lines, short-term priming with rosiglitazone enhances sensitivity to NECTIN4-CAR T cells, without increasing potential on-target, off-tumor toxicity to normal skin keratinocytes or normal bladder epithelial cells." (PMID 40931013, 2025). "Frequent concomitant detection of serum Nectin-4 with CEA and/or CA15.3 may suggest that circulating Nectin-4 comes directly from tumor cells and not from an indirect process such as immune response." (PMID 17474988, 2007). "Short course treatment with rosiglitazone did not alter RT112 tumor xenograft growth when compared to vehicle plus NTD T cells, suggesting that rosiglitazone alone does not affect RT112 tumor xenograft growth, but does enhance NECTIN4-CAR T cell efficacy and overall survival." (PMID 40931013, 2025). "Finally, other MV entry receptors may exist, as some tumor cell lines which do not express CD46, CD150/SLAM and nectin-4 are sensitive to MV infection." (PMID 24832799, 2013).
cancer (126 papers, 2007 to 2026). A tumor composed of atypical neoplastic, often pleomorphic cells that invade other tissues. "Nectin-2 and Nectin-4 are cell adhesion molecules associated with the progression of various cancers." (PMID 40699695, 2025). "The wild-type measles-associated receptor, Nectin-4, is a cell adhesion molecule that can be overexpressed in various malignant tumors, including BC." (PMID 39342391, 2024). "In summary, BT8009 offers a promising alternative to traditional ADCs for targeting Nectin-4 and other cancer-associated molecules." (PMID 38606099, 2024). "This review aims to compile and summarize the current state of research on Nectin-4, focusing on its diagnostic utility, prognostic significance, and its role in cancer treatment." (PMID 38606099, 2024). "Overexpression of Nectin-4 is reportedly implicated in disease progression and poor prognosis in several types of cancer." (PMID 32751328, 2020). "Patients with strong Nectin-4-expressing tumors had a significantly higher risk of progression (p = 0.031) and cancer-specific mortality (p = 0.036)." (PMID 32751328, 2020). "The underlying molecular mechanism of abnormal Nectin-4 expression in cancer progression still remains to be further investigated." (PMID 31043861, 2019). "Recent studies have reported that the Nectin-4 is over-expressed in multiple human cancers, and such abnormal expression is associated with cancer progression and poor prognosis of the patients." (PMID 31043861, 2019). "One such TNBC-specific cell surface molecule is Nectin-4 (also known as PVRL4), which has previously been described as a new tumor-associated antigen in a number of different carcinomas." (PMID 31572728, 2019). "Clinical trials are underway to target carcinomas that express Nectin-4 by use of this drug-linked monoclonal antibody (mAb) against Nectin-4." (PMID 28038455, 2017). "It was also demonstrated that a soluble form of Nectin-4 has a potential as a diagnostic marker for several cancers." (PMID 25888293, 2015). "ALDH3A1 and NECTIN4 have been previously linked to cancer pathogenesis." (PMID 39969205, 2025). "Similarly, tubulin alpha chain 1C (TUBA1C), adhesion G‐protein coupled receptor G2 (ADGRG2), and nectin‐4 have been associated with cell migration and proliferation, albeit in cancer cell types." (PMID 39895030, 2025). "Therefore, NECTIN‐4 emerges as a promising diagnostic and therapeutic target in different types of cancers." (PMID 39072867, 2024). "Nectin-4 is associated with poor outcomes in various other cancers." (PMID 38606099, 2024). "Generally, overexpression of nectin-4 in cancer tissues is linked to a worse prognosis." (PMID 37568798, 2023). "The overexpression in cancer was significantly associated with worse OS, and it was suggested that nectin-4 could be a prognostic factor in EC." (PMID 37568798, 2023). "Nectin-4 was highly expressed in tumors and was associated with more aggressive cancers." (PMID 37568798, 2023). "Tissue factor, TROP2, and NECTIN4 membranous expression were cancer-cell specific and strong (3+) in 29 %, 37 %, and 4 %, and high (≥2+) in 48 %, 68 %, and 12 % of tumors, respectively." (PMID 40577962, 2025). "In some types of cancer, increased expression of nectin-4 turns out to be a positive prognostic factor." (PMID 40244005, 2025). "EV is an antibody–drug conjugate (ADC) composed of the antibody enhortumab vedotin recognizing nectin-4 expressed on cancer cells and protease-cleavable linker-bound monomethyl auristatin E (MMAE), which disrupts microtubule formation." (PMID 39891702, 2025). "The cell adhesionprotein nectin-4 emerged as a valid therapeutictarget for antibody- and peptide-drug conjugates in cancer." (PMID 41081542, 2025). "NECTIN4 expression is observed in several other cancer types predominated with squamous histology with prevalence of high expression (moderate/strong) varying from 60 % in bladder cancer, 33 % in head and neck tumors, to 11 % of penile cancer." (PMID 40577962, 2025).
cancer (continued). "In the related literature, it is most commonly reported that in cancers, there is an increase in the cytoplasmic expression of nectin-4." (PMID 40244005, 2025). "This underscores the necessity for a comprehensive investigation of nectin-4 expression across a wide range of cancer types." (PMID 40244005, 2025). "Such discrepancies in the significance of nectin-4 for patient prognosis across a variety of cancer types serve as the basis for studying its expression in other types of cancers." (PMID 40244005, 2025). "Our study focuses on LSCC, providing new insights into the roles of Nectin-2 and Nectin-4—both of which remain relatively underexplored in this particular cancer type." (PMID 40699695, 2025). "In a recent large cohort analysis, high nectin-4 expression correlated with improved cancer-specific survival (CSS), while increased TROP2 expression was associated with early disease progression." (PMID 41228204, 2025). "Enfortumab vedotin (EV) is an antibody‐drug conjugate that selectively binds to the transmembrane protein Nectin‐4, which is highly expressed in various cancers, including UBC." (PMID 39801278, 2025). "Tissue factor, TROP2, and NECTIN4 are emerging ADC targets in various cancers but are underexplored in CC." (PMID 40577962, 2025). "Our findings, supported by existing research, reinforce the importance of Nectin-4 in cancer biology." (PMID 40699695, 2025). "Nectin-4, a transmembrane protein overexpressed in various cancers, plays a pivotal role in tumorigenesis and metastasis." (PMID 40542857, 2025). "On the other hand, the interaction between TIGIT and CD226 attenuates immune operations, while nectin-2 and nectin-4 are identified as promising targets in cancer treatment due to their effects on the behavior of tumor cells." (PMID 40777027, 2025). "Leveraging the biological characteristics of Nectin-4, antibody-drug conjugates (ADCs) developed targeting Nectin-4 have demonstrated significant efficacy in cancer treatment." (PMID 38755613, 2024). "The utility of nectin-4 as target in cancer led us to develop a novel nectin-4 ADC (ETx-22) with the aim of improving efficacy and tolerability compared with available therapy." (PMID 39440991, 2024). "Nectin-4 is an effective prognostic indicator for specific cancers and represents a valuable targetable biomarker in oncology in the limited armamentarium against cancer." (PMID 39440991, 2024). "Nectin-4 is overexpressed in many cancers and is mainly investigated as antibody-drug conjugate (ADC) target, i.e., as a tumor-associated antigen (TAA)." (PMID 38773064, 2024). "Nectin-4 is a Ca2+-independent immunoglobulin-like protein that exhibits significantly elevated expression in malignant tumors while maintaining extremely low levels in healthy adult tissues." (PMID 38606099, 2024). "NECTIN4-amplified samples or those with gains showed increased NECTIN4 mRNA levels compared with diploid samples on the pan-cancer level." (PMID 38657187, 2024). "The CAR-T cells are then infused back into the patient, where they can attack and kill cancer cells that express nectin-4." (PMID 40836974, 2024). "As a type I transmembrane protein that is aberrantly expressed in several cancer types, nectin-4 (also known as PVRL4) has emerged as a highly promising target for ADC research and development." (PMID 38664366, 2024). "In the phase I/II BT8009-100 trial, 49 patients with advanced cancers expressing Nectin-4 were treated with BT8009, resulting in an ORR of 50%." (PMID 39764422, 2024). "This overexpression is associated with enhanced cell proliferation, survival, and angiogenesis, making Nectin-4 a promising antigen target for cancer therapies, such as antibody-drug conjugates (ADCs)." (PMID 39598456, 2024). "This therapeutic approach works by delivering the microtubule-disrupting agent monomethyl auristatin E (MMAE) directly into cancer cells upon binding to Nectin-4, ultimately triggering apoptosis." (PMID 39764422, 2024).
cancer (continued). "In conclusion, Nectin-4 is a highly valuable molecular target in cancer, deserving further research and development." (PMID 38606099, 2024). "It is expected that research on Nectin-4 in the field of cancer therapy will continue to grow and progress." (PMID 38606099, 2024). "Nectin-4 plays a significant role in cancer development, mediating several functions including cell proliferation, differentiation, migration, and invasion." (PMID 39337530, 2024). "Nectin-4, an overexpressed oncological target for various cancers, has been exploited to create antibody-drug conjugates (ADCs) to treat solid tumors." (PMID 38755613, 2024). "Zelenectide pevedotin (BT8009) is a bicycle toxin conjugate (BTC), that acts by releasing MMAE into Nectin-4 positive cells, inducing cancer cell death." (PMID 39764422, 2024). "This drug is designed to specifically target cancer cells that express Nectin‐4, leading to internalization of the ADC–Nectin‐4 complex and subsequent cleavage of MMAE." (PMID 39070179, 2024). "One such strategy is to use ADCs, which bind to nectin-4 on the surface of cancer cells and deliver a cytotoxicity payload directly to the cells." (PMID 40836974, 2024). "EV induced dose‐dependent inhibition of cell growth of NECTIN‐4 expressing cancer cells (LNCaP and 22Rv1), while NECTIN‐4‐negative PC‐3 cells were resistant to EV treatment (unpaired t‐test, p < 0.01)." (PMID 39072867, 2024). "Nectin-4 is particularly overexpressed in various cancers, including bladder, lung, ovarian, pancreatic, and gastric cancers." (PMID 37345201, 2023). "Once bound to Nectin-4, enfortumab vedotin is internalized by the cancer cells through receptor-mediated endocytosis." (PMID 37686503, 2023). "Another common target is nectin‐4, a type 1 transmembrane protein that belongs to a family of cell adhesion molecules that are highly expressed in a variety of cancers, particularly in UC." (PMID 38089409, 2023). "Cumulative evidence now indicates that the NECTIN4 gene is overexpressed in a variety of cancers, and that the nectin-4 protein is both a disease marker and therapeutic target in a subset of these cancers." (PMID 37554937, 2023). "More recently, a study further identified nectin-4 as a cancer-specific ligand of the inhibitory receptor T-cell immunoreceptor with Ig and ITIM domains (TIGIT), and their interaction was found to inhibit the antitumor activity of nature killer (NK) cells." (PMID 38288120, 2023). "Nectin-4 was mostly overexpressed in cancer, and higher expression correlated with worse OS and was a prognostic factor." (PMID 37568798, 2023). "Our findings align with those of a recently published meta-analysis investigating the prognostic implications of nectin-4 across various cancer types." (PMID 37958883, 2023). "Previous studies have investigated the potential of Nectin-2 and Nectin-4 as biomarkers and treatment targets in various cancer types." (PMID 37174031, 2023). "In another study on GC, nectin-4 was also found to be upregulated in cancer compared to the adjacent tissues and was highly expressed in 70% of samples." (PMID 37568798, 2023). "Nectin-4 showed abundant expression in PDAC: 56.1% of tumors were classified as high-expressing cancers." (PMID 37568798, 2023). "As the ADC directly targets the Nectin-4 molecule, the Nectin-4 expression on cancer cells is relevant for the efficacy of this class of drugs." (PMID 36139571, 2022). "In conclusion, our small-molecule-based screening has identified two human cancer-related genes (Nectin-4 and CapG), whose translation is suppressed by the RNA G-quadruplexes." (PMID 35801908, 2022). "BT8009 is another bicycle peptide–toxin conjugate targeting nectin-4 for treatment of malignant tumors." (PMID 35890274, 2022). "The approach described in the present study allowed us to identify two human-cancer-related genes (Nectin-4 and CapG), whose translation is suppressed by the RNA G-quadruplexes." (PMID 35801908, 2022).